Y_RNA (Y RNA )
Gene: Miscellaneous RNA gene on chromosome 3 (49,270,132 to 49,270,239, forward strand). Ensembl gene ENSG00000199546.
Homologues: Orthologues: chimpanzee Y_RNA (100% identical), macaque Y_RNA (86% identical). Paralogues in human: RNY1 (81% identical), Y_RNA (81% identical), Y_RNA (80% identical), Y_RNA (79% identical), RNY1P10 (78% identical), Y_RNA (78% identical), Y_RNA (77% identical), RNY1P11 (76% identical), Y_RNA (76% identical), RNY1P8 (75% identical), Y_RNA (75% identical), Y_RNA (74% identical), and 94 more.